RMND1 (required for meiotic nuclear division 1 homolog)
Description:
Required for mitochondrial translation, possibly by coordinating the assembly or maintenance of the mitochondrial ribosome.
Synonyms: C6orf96; bA351K16.3; FLJ20627; RMD1; COXPD11; bA351K16
Tractability: PROTAC: ubiquitination databases record sites on it; its protein half-life has been measured.
Gene: Protein-coding gene on chromosome 6 (151,398,898 to 151,452,158, reverse strand). Ensembl gene ENSG00000155906.
Subcellular location: Mitochondrion
Subcellular location (Human Protein Atlas): Mitochondria
Gene Ontology:
Molecular function: protein binding
Biological process: positive regulation of mitochondrial translation
Cellular component: mitochondrion
Genetic constraint (gnomAD): Loss-of-function variants: 12 observed, 22.85 expected, observed/expected ratio (o/e) 0.53, 90% interval 0.34 to 0.85. The upper end of that interval is the gene's LOEUF score, 0.85, which puts it in group 3 of 6, group 1 being the genes least tolerant of losing a copy. Missense variants: 256 observed, 309.68 expected, observed/expected ratio (o/e) 0.83, 90% interval 0.75 to 0.92. Synonymous variants: 115 observed, 116.66 expected, observed/expected ratio (o/e) 0.99, 90% interval 0.85 to 1.15.
Gene-disease validity (ClinGen):
ClinGen rates the evidence that RMND1 causes each of these diseases.
mitochondrial disease (autosomal recessive): Definitive.
Homologues: Orthologues: chimpanzee RMND1 (99% identical), macaque RMND1 (96% identical), dog RMND1 (87% identical), rabbit RMND1 (86% identical), pig RMND1 (85% identical), mouse Rmnd1 (82% identical), rat Rmnd1 (81% identical), tropical clawed frog rmnd1 (56% identical), zebrafish rmnd1 (54% identical), Drosophila melanogaster CG11679 (30% identical), Caenorhabditis elegans ZK1010.2 (23% identical).
Diseases named in the same sentence as RMND1 in open-access papers:
RMND1 is named in the same sentence as 38 diseases in open-access papers, as found by Europe PMC text mining. Sharing a sentence is not in itself a finding about the gene and the disease. The quoted sentences say what the papers report.
Perrault syndrome (5 papers, 2020 to 2025). Perrault syndrome (PS) is characterized by the association of ovarian dysgenesis in females with sensorineural hearing impairment. "Our study provides an independent confirmation on the causative role of RMND1 in Perrault syndrome with renal involvement." (PMID 32911714, 2020). "This highlights the importance of including RMND1 to the list of Perrault syndrome causative factors and provides new insight into the clinical manifestation of RMND1 deficiency." (PMID 32911714, 2020). "In 2018, a different clinical presentation consistent with a diagnosis of Perrault syndrome (PRLTS) was associated with a known RMND1 (c.713A>G; p.Asn238Ser) homozygous variant." (PMID 32911714, 2020). "Our study presents the mildest, so far reported, RMND1-related phenotype and delivers the first independent confirmation that RMND1 is causally involved in the development of Perrault syndrome with renal involvement." (PMID 32911714, 2020). "Required for meiotic nuclear division 1 homolog (RMND1) is reported to be a pivotal player in mitochondrial transcription and its mutation may contribute to multiple diseases like Perrault syndrome, leukoencephalopathy, and severe renal hypoplasia." (PMID 38707433, 2024). "Notably, along with this PLN variant, a pathogenic variant was detected in Required for Meiotic Nuclear Division 1 homolog (RMND1) which might be responsible for the Perrault syndrome." (PMID 40556736, 2025).
breast carcinoma (4 papers, 2015 to 2021). "Several studies have suggested that the RMND1 gene is associated with human diseases, with lower RMND1 expression correlating with breast cancer risk and worse relapse-free survival, infantile encephalopathy, mitochondrial translation defects, hearing impairment, and renal failure." (PMID 31237926, 2019). "Furthermore, other genes at this locus including ARMT1, CCDC170, and RMND1 may also be candidates for an effect on breast cancer risk." (PMID 30642363, 2019). "In the estrogen receptor negative subtype of breast cancer, RMND1 expression is reduced in tumor samples associated with minor risk alleles but increased in those with major risk alleles, suggesting its possible dual role in breast cancer pathogenesis." (PMID 34361072, 2021).
deafness (3 papers, 2014 to 2022). An inherited or acquired condition characterized by the complete loss of the ability to hear from one or both ears. "One study performed an exome and plasma metabolome analysis of a child with mitochondrial kidney disease (RMND1 mutation) and deafness." (PMID 35323657, 2022).
renal failure (3 papers, 2016 to 2025). "We describe the phenotype of a child with novel compound heterozygous RMND1 gene variants and mitochondrial disease causing multisystem failure including renal failure and cardiomyopathy." (PMID 27350610, 2016).
chronic kidney disease (2 papers, 2016 to 2023). Impairment of the renal function secondary to chronic kidney damage persisting for three or more months. "Chronic kidney disease is a less common phenotype of nuclear mitochondrial gene mutations and has been reported in cases caused by mutations in COQ2, SARS2 and recently in RMND1 genes." (PMID 27350610, 2016).
developmental delay (2 papers, 2016). "The most common clinical features associated with RMND1 mutations were hypotonia (n=24, 75%) and global developmental delay (n=24, 75%) followed by sensorineural hearing loss (n=23, 72%) that was most frequently identified at neonatal hearing screening." (PMID 27412952, 2016). "We show that the congenital sensorineural deafness, central hypotonia, developmental delay and lactic acidaemia are cardinal clinical features associated with RMND1 mutations." (PMID 27412952, 2016). "Clearly, there are a wide range of clinical features associated with RMND1 mutations, but the frequency of occurrence for each clinical feature varies enormously, with hypotonia, developmental delay and sensorineural hearing loss being the obvious exceptions." (PMID 27412952, 2016). "We report the case of a child found to harbour compound heterozygous variants in the RMND1 gene, who presented with global developmental delay, truncal hypotonia, bilateral sensorineural hearing loss and renal impairment." (PMID 27350610, 2016).
lactic acidosis (2 papers, 2020 to 2023). Metabolic acidosis characterized by the accumulation of lactate in the body. "Pathogenic variants in RMND1 were originally described for a patient with combined oxidative phosphorylation deficiency 11 (COXPD11), characterised by neonatal hypotonia and lactic acidosis as well as infantile onset renal failure, hearing loss and multi-organ defects." (PMID 37946251, 2023).
Acidosis (1 paper, 2020). Abnormal acid accumulation or depletion of base. "The single, so far described, patient with PRLTS and RMND1 homozygous pathogenic variant had distal renal tubular acidosis with hyperchloremic metabolic acidosis, a normal anion gap, mildly elevated uric acid, low urine citrate levels, normal calcium levels, and a normal renal ultrasound." (PMID 32911714, 2020).
Arterial thrombosis (1 paper, 2024). The formation of a blood clot inside an artery. "Arterial thrombosis observed in patients 1 and 2 has not been described in RMND1 mutations." (PMID 37450011, 2024).
dilated cardiomyopathy (1 paper, 2016). Cardiomyopathy which is characterized by dilation and contractile dysfunction of the left and right ventricles. "We report RMND1 gene variants associated with end stage renal failure, dilated cardiomyopathy, deafness and neurological involvement due to mitochondrial disease." (PMID 27350610, 2016).
Kapur-Toriello syndrome (1 paper, 2023). Kapur-Toriello syndrome is an extremely rare syndrome characterized by facial dysmorphism, severe intellectual deficiency, cardiac and intestinal anomalies, and growth retardation. "The phenotypic spectrum of one gene, RMND1, was expanded to include polymicrogyria, whilst BMP4 is being investigated as a candidate for Kapur-Toriello syndrome." (PMID 37946251, 2023). "Additionally, one gene, RMND1, is novel for the phenotype of polymicrogyria whilst BMP4 is a putative novel gene for Kapur-Toriello syndrome which, if confirmed, would extend the phenotypic range of this gene from its current association with microphthalmia and clefting syndrome." (PMID 37946251, 2023).
renal dysplasia (1 paper, 2016). Renal dysplasia is a form of renal malformation in which the kidney(s) are present but their development is abnormal and incomplete. "This comprised of renal dysplasia in two patients homozygous for c.1349G>C, p.450Serext*32 stop-extension RMND1 mutation, one of which also had cardiac involvement." (PMID 27350610, 2016).
mitochondrial disease (6 papers, 2016 to 2025). "The nuclear encoded gene RMND1 (Required for Meiotic Nuclear Division 1 homolog) has recently been linked to RMND1‐related mitochondrial disease (RRMD)." (PMID 31568715, 2019). "The nuclear gene RMND1 has recently been implicated in mitochondrial disease, but the spectrum of pathogenic variants and associated phenotype for this gene, has not been fully elucidated." (PMID 27350610, 2016). "Recently, the nuclear encoded RMND1 gene has been implicated in causing mitochondrial disease of varying severity, manifesting in profound deafness and neurological involvement with or without renal and cardiac manifestations." (PMID 27350610, 2016). "This case expands current knowledge of mitochondrial disease secondary to mutation of the RMND1 gene by further delineating renal manifestations including histopathology." (PMID 27350610, 2016). "Mutations in the RMND1 (Required for Meiotic Nuclear Division protein 1) gene have recently been linked to infantile onset mitochondrial disease characterised by multiple mitochondrial respiratory chain defects." (PMID 27412952, 2016). "RMND1 gene mutations have been linked to mitochondrial disease with varying severity and variable multisystem involvement." (PMID 27350610, 2016). "Patients with RMND1‐related mitochondrial disease have a significantly higher likelihood of developing kidney disease, potentially due to the enrichment of mitochondria in renal tubular cells (due to high ATP demands)." (PMID 40236310, 2025). "RMND1‐related mitochondrial disease is a rare genetic condition that affects multiple organs, including the kidneys." (PMID 40236310, 2025). "Due to a strong clinical suspicion of mitochondrial disease, nuclear genetic studies were undertaken, prioritising the analysis of the RMND1 gene because of the clinical presentation." (PMID 27350610, 2016). "More recently, case reports have described patients presenting with a more varied and, in some cases, milder phenotype; these reports have proposed new condition names such as “RMND1‐related mitochondrial disease” and “Perrault‐like syndrome” to underscore the spectrum of findings." (PMID 40236310, 2025).
tumor (4 papers, 2018 to 2021). "RMND1 is a potential tumor suppressor, as it is downregulated in chronic myeloid leukemia." (PMID 34361072, 2021).
kidney disease (2 papers, 2016 to 2025). "RMND1‐related kidney disease can include tubulopathies, renal tubular acidosis, interstitial nephritis and may progress to end‐stage kidney disease (ESKD)." (PMID 40236310, 2025).
RMND1 also shares sentences with these, for which no sentence is quoted: cardiomyopathy (2 papers); Hearing impairment (2); hyperkalaemia (2); hyponatraemia (2); ovarian dysfunction (2); arthrogryposis (1); Bartter syndrome type 4A (1); breast tumors (1); chronic myeloid leukemia (1); congenital sensorineural deafness (1); distal renal tubular acidosis (1); encephalomyopathy (1); end stage renal failure (1); Hypergonadotropic hypogonadism (1); Infantile encephalopathy (1); Leukoencephalopathy (1); liver failure (1); microphthalmia (1); myopathy (1); pancreatitis (1); polymicrogyria (1); sensorineural deafness (1); sideroblastic anaemia (1).